IL33 (interleukin 33)
Diseases named in the same sentence as IL33 in open-access papers (continued):
Sharing a sentence is not in itself a finding about the gene and the disease.
kidney disease (16 papers, 2016 to 2024). "We found a connection between IL-33 and the residual risk of kidney disease progression on top of standard-of-care in patients with DKD and significant subclinical inflammation." (PMID 38899206, 2024). "The IL-33/ST2 axis has been implicated in renal diseases, including DN, in both clinical and animal studies." (PMID 38053041, 2023). "In a word, the progression of renal disease is associated with the sustained activation of IL-33/ST2." (PMID 35046838, 2021). "Recently, several studies have suggested that IL-33 is involved in the pathogenesis of kidney diseases and the associated tissue reparative responses." (PMID 32102434, 2020). ",40,50,74, 75, 76, 77, 78 In several mouse models of renal disease, blocking IL-33 has also been shown to reduce disease severity." (PMID 38899206, 2024). "It is currently believed that the progression of kidney disease is closely related to the persistent activity of IL-33/ST2." (PMID 36859530, 2023). "The ILC2-activating cytokine IL-33 is released from epithelial cells upon tissue damage, and it is upregulated in various kidney disease mouse models and in kidney disease patients." (PMID 34381446, 2021). "Other effective natural compounds targeting IL-33/ST2 still need to be discovered for the treatment of kidney diseases." (PMID 35046838, 2021). "Overall, the involvement of ST2 seems to be more predictive than IL-33, especially in investigating the deterioration of kidney function; however, both compounds are pivotal in the field of renal diseases." (PMID 30769901, 2019). "In this review, we discuss the pathological and tissue reparative roles of the IL-33/ST2 pathway in different types of renal diseases." (PMID 28387719, 2017). "Better understanding of the pathological role of IL-33 in kidney diseases will help in the development of novel therapeutic strategies for treating or preventing kidney diseases." (PMID 28387719, 2017). "Below, we focus on recent findings of the IL-33/ST2 axis involved in renal diseases in human and animal models." (PMID 28387719, 2017). "There were few studies conducted regarding IL-33/ST2 and cardiovascular risk in patients with kidney disease." (PMID 28614418, 2017). "Several lines of evidence both from clinical and animal studies demonstrate that the IL-33/ST2 axis is involved in renal diseases." (PMID 28387719, 2017). "Antibody-mediated systemic inhibition of IL-33 signaling in T2D mice with reduced kidney function and proteinuria (db/db unx) was then sufficient to reduce endothelial inflammation, improve glomerular health, and attenuate overall kidney disease progression." (PMID 38899206, 2024). "Although ILC2s account for approximately 1% of total renal leukocytes, IL-33 expression is upregulated in several kidney disease models, indicating that renal ILC2s are potentially activated and exert unknown functions at both the acute and chronic phases." (PMID 34381446, 2021). "IL-33-ST2 signaling is upregulated by various kidney injuries and diseases, leading to the activation of ILC2s in the kidney; however, it likely depends on the amount of IL-33 whether ILC2s play a protective or progressive role in renal disease." (PMID 34381446, 2021). "In conclusion, blocking the IL-33/ST2 pathway may be a novel therapeutic strategy for treating renal diseases in the future." (PMID 35046838, 2021). "However, there is limited information about TCM targeting the IL-33/ST2 pathway in the treatment of kidney diseases." (PMID 35046838, 2021). "However, with prolonged research in this field, it is expected that the IL-33/ST2 pathway will be used as a diagnostic and prognostic tool for renal diseases." (PMID 35046838, 2021). "The optimization of the timing, dosages, and tissue specificity may be crucial for the development of IL-33-based therapeutics for treating various kidney diseases, such as AKI." (PMID 32102434, 2020).
kidney disease (continued). "Additionally, many clinical studies have revealed that the IL-33/ST2 pathway may be an effective biomarker of kidney disease, and this is important for the early diagnosis of CKD and assessment of patient prognosis." (PMID 35046838, 2021). "Hence, it is unclear whether IL-33 can be used as a reference indicator in patients with kidney disease." (PMID 35046838, 2021). "Although recent studies have revealed the mechanism of IL-33–related immune responses and type 2 immunity in allergic conditions, the role and function of IL-33 and ST2 in kidney diseases is poorly understood." (PMID 37907612, 2023). "Some studies have shown that the expressions of IL-33 and ST2 are elevated in various renal disease models." (PMID 38053041, 2023). "In recent years, the levels and functions of IL-33 and ST2 in renal diseases have been the subject of research." (PMID 28614418, 2017). "The levels of IL-33 and soluble ST2 are generally tested to evaluate severity and prognosis of renal diseases clinically." (PMID 28387719, 2017).
metabolic disorders (16 papers, 2016 to 2026). "Recently, intestinal IL-33 promoted microbiota-derived trimethylamine N-oxide synthesis and accelerated MASLD progression, whereas global or intestinal deletion of Il33 in mice ameliorated metabolic disorders, inflammation, and fibrosis associated with MASLD." (PMID 40494889, 2025). "Evidence for the correlation between circulating levels of IL–33 and IL–37 in MetS and its associated metabolic disorders in human adults is scarce." (PMID 38255771, 2024). "Our analyses indicate that the current evidence is insufficient to reliably determine a direct association for IL-33 with changes in inflammatory conditions in metabolic disorders." (PMID 39171751, 2024). "Given that chronic low-grade inflammation is a hallmark of metabolic diseases, IL-33 has the potential to be used as a biological agent due to its role as an immunoregulatory cytokine with the capacity to suppress inflammatory responses." (PMID 39171751, 2024). "Taken together, and as seen from the results of our meta-analysis, it currently remains difficult to draw any firm conclusions about the role of IL-33 in human metabolic disease." (PMID 39171751, 2024). "The use of animal models to study the role of IL-33 in metabolic disease has revealed a protective role for IL-33, following the demonstration of anti-inflammatory and prohomeostatic properties within adipose tissue." (PMID 39171751, 2024). "Circulating levels of IL-33 were significantly elevated in overweight/obese Chinese adults with metabolic disorders." (PMID 33541367, 2021). "The IL-33/sST2 axis appears to play a role in metabolic disorders, but this theory is based primarily on in vitro studies and in vivo studies in animals." (PMID 33608010, 2021). "This review highlights the function of IL-33/ST2 axis on different immune cells in the metabolic disorders." (PMID 30761089, 2019). "Due to the vital role of IL-33 in the metabolic homeostasis, a sound understanding of the production, regulation, and function of IL-33 will facilitate the treatment of metabolic disorders." (PMID 30761089, 2019). "Except regulating the function of immune cells including T cells, B cells, dendritic cells (DCs), macrophages, mast cells, and innate lymphoid cells, IL-33 also plays an important role in metabolic diseases and has received an increasing attention." (PMID 30761089, 2019). "IL-33 has been shown to have a positive role in regulating the thermogenic capacity of adipose tissue and presents an attractive target for interventions aimed at combating metabolic disease." (PMID 39171751, 2024). "This study could provide new insight for further research on IL-33 as a new intervention target for metabolic disorders." (PMID 38632591, 2024). "In comparison, human studies exploring the role of IL-33 in adipose tissue have provided much more varied insights into the potential role of IL-33 in modulating the inflammatory processes that accompany the onset of metabolic disease." (PMID 39171751, 2024). "Further, we speculate that the kinetics of innate and/or adaptive immune cell responses, such as Th2 and Treg cells which are protective against metabolic disease, may be regulated by the ratio of IL-33 to ST2." (PMID 31073344, 2019). "Fourth, the IL-33 expression in adipose tissues of the participants was unable to detect in this study; Future research on the role of IL-33 in metabolic diseases from the perspectives of comparing tissue levels and circulatory levels will help to further reveal its action on metabolic disease." (PMID 33541367, 2021). "This study demonstrated that IL-33 was an important regulator of preadipocyte differentiation and inhibited adipogenesis by regulating the Wnt/β-catenin/PPAR-γ signaling pathway, which provided a new insight for further research on IL-33 as a new intervention target for metabolic disorders." (PMID 38632591, 2024).
metabolic disorders (continued). "Additionally, since the temporal relationship between serum level of IL-33 and the occurrence of metabolic disorders in overweight/obese population was not known, we cannot conclude that IL-33 directly causes metabolic disorders in overweight/obese patients." (PMID 33541367, 2021). "Therefore, there appears to be some potential dynamic between IL-33 and the TLR system, specifically TLR3 and TLR9, during the development of metabolic disease, which may be impacted by glucose-lowering medications." (PMID 31073344, 2019).
neurodegenerative disease (16 papers, 2006 to 2025). A disorder of the central nervous system characterized by gradual and progressive loss of neural tissue and neurologic function. "The present work summarizes the structure of IL-33, its fundamental activities, and its role in immunoregulation and neurodegenerative diseases." (PMID 37892176, 2023). "The IL-33/ST2 pathway plays a crucial role in neurodegenerative diseases and is activated by tissue injury, fibrosis, remodeling, and inflammation; moreover, the pathway participates in the homeostasis or pathogenic mechanisms of such disorders." (PMID 37892176, 2023). "The clinical application and mechanism of IL-33 in neurodegenerative diseases still require further investigation." (PMID 37892176, 2023). "For example, IL-33 signaling has been demonstrated to play diverse but significant roles in the homeostasis of the central nervous system diseases such as neurodegenerative diseases." (PMID 35729600, 2022). "Our previous studies have shown that IL-33 can regulate macrophage metabolism by influencing its polarization, and therefore the role of IL-33 on mtDNA and microglia in neurodegenerative diseases is worthy of our next investigation." (PMID 34943020, 2021). "Collectively, the study suggested that apigenin and luteolin’s regulation of signaling pathways contributed to the inhibition of IL-31 and IL-33, thus suggesting its importance for the improvement of neurodegenerative diseases involving these two cytokines." (PMID 32204450, 2020). "The alarmins and signaling pathways more frequently associated with the neurodegenerative diseases comprise β-amyloid, α-synuclein, defensins, exogenous S100B, HMGB1, Hsp, and IL-33." (PMID 33114371, 2020). "Rather, modulation of IL-33 production in CNS would appear to be the most appropriate course of action for treating neurodegenerative diseases involving IL-33." (PMID 32204450, 2020). "IL-33 also plays a dual role in neuroprotection and neurotoxicity in neurodegenerative diseases." (PMID 37892176, 2023). "The long-term safety and efficacy of IL-33 systemic administration in humans for neurodegenerative diseases such as AD remain unclear." (PMID 37892176, 2023). "Specifically, the expression level of IL-33 may vary from the different pathogeneses in the different subtypes of the various neurodegenerative diseases." (PMID 37892176, 2023). "The precise pathophysiological activity of the IL-33/ST2 signaling pathway in neurodegenerative diseases should be further explored, and IL-33 could be a promising prognostic marker and therapeutic target for neurodegenerative disorders." (PMID 37892176, 2023). "IL-33 is an important immune mediator in various disorders including neurodegenerative diseases." (PMID 31450606, 2019). "The IL-33/ST2 pathway is involved in CNS homeostasis and its pathologies, including neurodegenerative diseases." (PMID 35912090, 2022). "IL-33 as a promising target may provide new strategies for the treatment of TBI and neurodegenerative diseases in the future." (PMID 40764944, 2025). "Therefore, IL-33 is a critical regulator of TNF-α-induced functions in RA-SFs, pointing to a central role of this cytokine in the perpetuation of pro-inflammatory and pro-destructive processes in RA and other inflammatory and degenerative diseases." (PMID 22246057, 2012).
adenocarcinoma (14 papers, 2008 to 2025). A common cancer characterized by the presence of malignant glandular cells. "The inflammatory content of the microenvironment increases IL-33 transcript in CAFs, whose levels are associated with increased cell migration, whilst activating the onset of a migrating mesenchymal phenotype in an adenocarcinoma cell line." (PMID 31281317, 2019). "Expression of IL-33 in adenocarcinomas and its relationship with clinical pathological characteristics of NSCL." (PMID 29499051, 2018). "Although several high-grade adenocarcinomas showed a strong expression of IL-33 and ST2, both proteins were predominately overexpressed in low-grade adenocarcinomas." (PMID 27148488, 2016). "We found abundant expression of IL-33 in the nucleus of CD31+ or vWF+ endothelial cells from blood vessels in adenocarcinomas of the kidney, stomach, liver, pancreas, lung, breast or colon (data not shown)." (PMID 18836528, 2008). "Interestingly, the expression of ST2, a specific receptor of IL-33, was also down-regulated in both adenocarcinoma and squamous cell carcinoma tumor tissues when compared to their matching adjacent normal lung tissues." (PMID 29499051, 2018). "For example expression levels of IL-33 and ST2 were significantly down-regulated in both adenocarcinoma and squamous cell carcinoma of lung tissues when compared to adjacent normal lung controls." (PMID 30483263, 2018). "In CRC patients, we found overexpression of both IL-33 and ST2 in intestinal adenomas and adenocarcinomas." (PMID 27148488, 2016). "Interestingly, increased expression levels of IL-33 and ST2 were more frequently observed in low-grade adenocarcinomas than high-grade adenocarcinomas." (PMID 30547011, 2018).
lung (13 papers, 2014 to 2024). "Innate lymphoid cells from EA exhibited stronger proliferation in vitro, with IL‐33 inducing the pulmonary accumulation and rapid activation of ILC2s, consequently aggravating lung allergic inflammation." (PMID 37357549, 2023). "Their results strongly suggest that ST2 is a key mediator for IL-33 induced colorectal tumorigenesis." (PMID 30547011, 2018). "Neutrophil serine proteases play a significant role in regulating the bioactivity of IL-33 in sterile neutrophilic inflammation, which plays a vital role in the pathogenesis of acute ischemia-induced injuries, acute lung and liver injuries, and chronic lung, bowel, and joint diseases." (PMID 39085349, 2024).
central nervous system diseases (10 papers, 2017 to 2026). "Future research needs to be conducted into utilising the IL-33/ST2 pathway as a therapeutic target for disorders of the central nervous system." (PMID 38694387, 2024). "Interleukin-33 (IL-33) regulates immune responses in central nervous system diseases." (PMID 41483148, 2026). "Moreover, a recent study has showed that IL‐33 was highly expressed in the spinal cord and brain and played critical roles in central nervous system diseases (Han, Mi, & Wang, 2011)." (PMID 31397082, 2019). "Currently, there are no clinical studies employing IL-33/ST2 signalling to treat CNS disorders." (PMID 38694387, 2024).
colon (6 papers, 2019 to 2024). "The partially unraveled role of IL-33/ST2 signaling in gastrointestinal tract cancers is being investigated through the analysis of patients’ samples and by studies in murine and rat models." (PMID 37296602, 2023). "It has been shown that IL‐33 and OPN are closely related to the development of digestive system tumors; therefore, we wondered whether either of them could represent a promising biomarker as a predictor of prognosis in CRC." (PMID 34664425, 2021).
intestinal disease (6 papers, 2017 to 2023). "In summary, our studies demonstrate that an extra intestinal disease can induce an inflammatory environment within the GI tract that leads to the production of IL-33 from stressed epithelial cell populations." (PMID 38042840, 2023). "Literature review on the role of IL-33 in the regulation of intestinal immunity, involvement in the intestinal disease, and implication in potential therapeutics." (PMID 34350086, 2021). "Recently, sST2 has been shown to be secreted by intestinal pro-inflammatory T cells during gut inflammation; on the contrary, protective ST2-expressing Tregs are decreased, implicating that ST2/IL-33 signaling may play an important role in intestinal disease." (PMID 28484466, 2017). "Not only does this demonstrate the importance of nuclear sequestration of IL-33 but also highlights the potency of IL-33/ST2 signaling in the acute inflammatory response and a potential role in intestinal disease." (PMID 31139196, 2019). "Despite potentially playing an important role as a mediator of mucosal immunity, and being suggested as a drug target for various disorders, there are currently no IL-33-based therapies for intestinal disease." (PMID 31139196, 2019).
Hematologic Malignancies (5 papers, 2015 to 2022). "In hematological malignancies, alarmins such as IL-33 and Hsp-70 are commonly released, and cytokines such as IL-1 have been found to activate MCs and cause the release of IL-6 and TNF-α, while chymase from MCs has been shown to degrade IL-33 and Hsp-70 due to their ability to cause inflammation." (PMID 34631562, 2021). "In the field of hematological malignancies, the role of IL-33 seems even more complex." (PMID 31652497, 2019). "Results showed that IL-33 effects in normal cells are rather modest and this suggests that this cytokine could be more effective in malignant cells than in normal ones, confirming once more the fundamental role of the IL-33/ST2 axis in hematologic malignancies." (PMID 31652497, 2019). "And finally, does manipulation of the IL-33/ST2 axis impair the GVL response, which determines the curative potential of alloHCT for hematologic malignancies?" (PMID 35703182, 2022). "However, the study of the effects of IL-33 on the different aspects of the physiopathology of hematological malignancies could help us to better understand the intimate mechanisms that regulate the onset and progression of these diseases and make their treatment easier." (PMID 31652497, 2019). "IL-33 has been shown to participate in different biological activities in both nonhematological and hematological malignancies." (PMID 34435521, 2021).